CXCL13 (C-X-C motif chemokine ligand 13)
Diseases named in the same sentence as CXCL13 in open-access papers (continued):
Sharing a sentence is not in itself a finding about the gene and the disease.
lupus (36 papers, 2010 to 2025). "CXCL13 is found in human blood, plasma and serum and high CXCL13 levels have been associated with pSS and systemic lupus erythematosus (SLE)." (PMID 32047959, 2020). "The critical roles of CXCL13 and CXCR5+ cells in the pathogenesis of LN are also evidenced by studies of anti-CXCL13 neutralizing antibodies in MRL/lpr lupus-prone mice and CXCR5-deficiency in B6/lpr lupus-prone mice." (PMID 27403037, 2016). "TLS formation in kidneys affected by lupus may be instigated by local increases in lymphorganogenic chemokines such as CXCL13, and in molecules associated with leukocyte migration and vascularization." (PMID 38022566, 2023). "In our lupus model, increasing proinflammatory cytokines such as Cxcl13, Ccl19, Ltβ, and Baff mRNA levels trigger the TLOs formation." (PMID 40651955, 2025). "Macrophages and renal DCs are reported to be the main sources of CXCL13 in lupus-prone mouse models." (PMID 35309354, 2022). "It is nonetheless notable that a sustained interferon signature and CXCL13 expression have been identified in the lung transcriptome of cSiO2-exposed lupus-prone NZBWF1 mice." (PMID 35983030, 2022). "In MRL/lpr lupus-prone mice, blockade of CXCL13 was found to significantly reduce spleen Th17/Tregs ratio, renal inflammatory cytokines production, and alleviated kidney damage." (PMID 35309354, 2022). "The aim of the present study was to inhibit CXCL13 and examine the effect of this intervention on lymphoid formation and the development of neurobehavioral manifestations in lupus mice." (PMID 34868008, 2021). "Perhaps the most prominent effect was in its normalization of plasma cytokines, several of which, such as CCL5/RANTES, CXCL2/MIP-2, CXCL12/SDF-1α, and CXCL13/BCA-1, were known biomarkers of lupus severity." (PMID 32582860, 2020). "Expression of CXCL13 was also detected in lupus and correlated with lupus disease activity measures." (PMID 26362815, 2015). "In patients with lupus nephritis (LN) and in lupus-prone mice, enhancedplasma levels of biglycan correlate with the abundance of circulating CXCL13 and theextent of albuminuria." (PMID 22821552, 2012). "The aberrantly high expression of CXCL13 in the thymus of mice with murine lupus plays a pivotal role in recruiting autoantibody-producing B cells." (PMID 20856892, 2010). "Resolution of TLS, along with improvement in lupus, by treating animals with soluble BAFF receptor, docosahexaenoic acid, complement inhibitor C4BP(β-), S1P1 receptor modulator Cenerimod, dexamethasone, and anti-CXCL13 further emphasizes a role of TLS in the pathogenesis of lupus." (PMID 38022566, 2023). "used neutralizing anti-CXCL13 antibodies to block MRL/lpr lupus-prone mice." (PMID 35309354, 2022). "Serum CXCL13 concentrations might represent a potential marker of disease activity in systemic lupus erythematosus." (PMID 34961474, 2021). "Especially if the TLS are an important contributing factor to the neuropsychiatric manifestations, targeting them by inhibiting certain components, such as CXCL13, or blocking certain functions, is worth pursuing further to develop more effective therapies for lupus and NPSLE." (PMID 34868008, 2021). "Moreover, in LNB, CNS lymphoma, lupus, and bacterial meningitis patients CXCL13 was also highly elevated in CSF suggesting a concurrent CNS and peripheral inflammation." (PMID 32089130, 2020). "Indeed, plasma CXCL13 was higher in patients with systemic lupus erythematosus and lupus nephritis and in patients with anti-neutrophil cytoplasmic antibody vasculitis with active disease while urinary CXCL13 was increased in antibody-mediated kidney graft rejection." (PMID 39188767, 2024). "SLE patients with lupus nephritis were reported to have significantly higher levels of serum CXCL13 than controls." (PMID 35371102, 2022).
lupus (continued). "The current study demonstrated that treatment with an anti-CXCL13 neutralizing antibody attenuated behavioral deficits in lupus-prone mice and could be doing so on a molecular level by altering expression levels of certain inflammatory mediators or direct effect on resident brain cells." (PMID 34868008, 2021). "CXCL13 has also been shown to be important in SLE; systemic levels of CXCL13 positively correlate with disease activity scores in SLE patients, and blocking CXCL13 in lupus mice attenuated renal disease." (PMID 34868008, 2021). "Clinically, serum level of CXCL13 was found higher in SLE patients and in positive correlation with disease activity, and Tfh was shown to facilitate GC reactions, thereby contributing to lupus pathogenesis in different murine models." (PMID 31546763, 2019). "As a CXC subtype member of the chemokine superfamily, CXCL13 is considered to be involved in systemic lupus erythematosus (SLE), especially in lupus nephritis (LN)." (PMID 27672667, 2016). "In Systemic lupus erythematosus patients, 391 disease‐specific chromatin loops are present, encompassing crucial inflammation‐ and immunity‐related genes, including DDX60L and CXCL13." (PMID 37426677, 2023). "Thus, neutralizing CXCL13 may also have diminished depressive-like behavior in lupus mice." (PMID 34868008, 2021). "The chemokines CCL2, CCL3, CCL5, CXCL10, CXCL12, CXCL13, and CX3CL1 are expressed in the nephritic kidney of lupus-prone mice and SLE patients and increase inflammatory cell infiltration into the kidney." (PMID 30057623, 2018). "Two different combined inflammatory and lymphoid chemokine scores were investigated using CCL2, CXCL10 and CCL19 (score used successfully in lupus) and CXCL9, CXCL10, CXCL13 and CCL19 data." (PMID 24278364, 2013). "Therefore, CXCL13/CXCR5 contributes to the development of LN both systemically in immune tissues and locally in the kidney of lupus-prone mice." (PMID 27403037, 2016). "In particular, specific neutralization of CXCL13 with anti-CXCL13 antibody can effectively decrease the Th17/Treg ratio in spleen, therefore alleviating kidney damage in MRL/lpr mice, which is a well-studied animal model for lupus and a generally accepted spontaneous model of LN." (PMID 41164191, 2025). "Renal macrophages and DC in lupus-prone mice may be the source of CXCL13 in the nephritic kidney, leading to increased migration of CXCR5+ B cells and TFH-like cells into the inflamed kidney towards CXCL13." (PMID 27403037, 2016). "In two commonly used lupus-prone mouse models, NZB/W F1 and MRL/lpr, transcript levels of renal CXCL13 and CXCR5 are consistently increased in aged lupus nephritic mice compared to nonlupus control mice or young mice prior to disease onset, suggesting their involvement in the development of LN." (PMID 27403037, 2016).
gastric cancer (35 papers, 2015 to 2025). A primary or metastatic malignant neoplasm involving the stomach. "With the levels of Tfh, Breg, and CXCL13 increased, related lymph node metastasis and poor prognosis have been observed in gastric cancer patients." (PMID 39744696, 2025). "In gastric cancer, enforced expression of CXCL13 is positively correlated with cancer progression and poor survival." (PMID 36612163, 2022). "The CXCL13/CXCR5 axis drives CD40+ MDSC migration to gastric cancer, leading to immune escape and tumor progression." (PMID 34947813, 2021). "CXCL13 abounds in the serum and tumor tissue of patients with gastric cancer and serves as a prognostic marker for patients under postoperative adjuvant chemotherapy." (PMID 34947813, 2021). "Some of these chemokines and receptors, such as CXCL13, CCL4, CCL5, CCR2, CXCR3, and CXCR4, have been experimentally confirmed to be associated with the pathogenesis or prognosis of gastric cancer or other malignancies." (PMID 32685487, 2020). "Consistent with observations in other cancers, serum levels of CXCL13 were higher in patients with gastric cancer compared to healthy individuals, and this correlates with a high number of circulating TFH cells." (PMID 31354634, 2019). "Also, CXCL13 and CXCR5 are implicated in tumor growth and metastasis, with CXCL13 serving as a predictive marker for chemotherapy response in advanced gastric cancer patients." (PMID 40445003, 2025). "They found that activated B cells could stimulate the mTOR signaling pathway in CD103+CD8+ Trm cells through the LTα-TNFR2 signaling axis, promoting glycolysis and the secretion of CXCL13 and granzyme B, which in turn kills gastric cancer cells." (PMID 39840050, 2024). "Another research discovered that circulating follicular helper T (cTfh) cells and their related factors (IL-21/CXCL13) may have a role in the development and progression of gastric cancer." (PMID 36793271, 2023). "CXCL13 has been reported as a prognostic factor in gastric cancer." (PMID 36650632, 2023). "Tfh%, Breg%, and CXCL13 level were significantly increased among gastric cancer patients." (PMID 36339942, 2022). "Our findings indicated that Tfh and Breg subsets along with CXCL13 might participate in the pathogenesis of gastric cancer." (PMID 36339942, 2022). "High infiltration of CXCL13+ CD8+ T cells in tumor tissue is associated with poor clinical outcomes for the patients, and elimination of these cells could be helpful for gastric cancer immunotherapy." (PMID 34947813, 2021). "In leukemia, prostate, lung, pancreatic, colon, and gastric cancers, CXCL13 exhibits pro-cancer effects by recruiting B cells, CD68+ macrophages, regulatory B cells (Bregs), Treg, and CD40+ MDSCs, shaping an immune-suppressive TME to trigger tumorigenesis and tumor progression." (PMID 34947813, 2021). "Notably, a transcriptome analysis of biopsies from gastric cancer patients revealed significant up-regulation of CXCL13, which is mainly expressed in isolated lymphoid follicles and small lymphoid aggregates." (PMID 31354634, 2019). "In gastric cancer, CXCL13 expression is predictive of shorter overall survival." (PMID 31354634, 2019). "Also, high expression of CXCL13 worsens the prognosis of gastric cancer after resection." (PMID 37304286, 2023). "Moreover, CXCL13 expression stratified gastric cancer patients in T2–4 stage." (PMID 36612163, 2022). "In the comparison of metabolite interference group and M2 group marker proteins in gastric cancer cells, there were significant differences in CCL17, CCL18 and CXCL13." (PMID 39991579, 2025). "In the field of GI cancer, a promalignant role of the CXCL13/CXCR5 axis has been shown for pancreatic cancer and gastric cancer as well as hepatocellular carcinoma." (PMID 36077611, 2022). "In a mouse model of spontaneously developing gastric cancer by activated STAT3 signaling, chemokines CXCL13, CCL19, and CCL21 were induced simultaneously with tumorigenesis and TLS formation." (PMID 35552285, 2022).
gastric cancer (continued). "Intratumoral CXCL13+ CD8+ T cells orchestrate immune-evasive actions, which consist of increased regulated Tregs and exhausted cytotoxic T cells in gastric cancer." (PMID 34947813, 2021). "The mRNA levels of RAI14, GUCY1A2, CNGB3, FJX1, FZD2, ELOVL2, and GDPD4 were all expressed upregulated in gastric cancer tissues, except for CXCL13, whose expression level was not significantly different between gastric cancer tissues and normal cell lines." (PMID 36823639, 2023). "Six of them (β-catenin, C-MYC, CXCL13, DC-SIGN, EGFR, and PIM2) are consistently described as oncogenes according to the literature, and are overexpressed at the protein or mRNA level in gastric tissue among infected children and gastric cancer patients." (PMID 32117120, 2020).
CNS lymphoma (33 papers, 2013 to 2026). "Studies in rapidly progressing CNS lymphoma (CNSL) have recently confirmed the excellent diagnostic utility of CXCL13 as well as CXCL9 as predictors of diagnosis, severity of the clinical presentation, and response to therapy." (PMID 38674602, 2024). "Their result demonstrated that elevated concentration of the chemokine CXCL13 concentration in CSF is a highly specific marker for the detection of CNS lymphoma and can be helpful as an adjunctive diagnostic test and response to treatment assessment." (PMID 33925295, 2021). "The typical diagnostic workup for CNS lymphoma consists of CSF analysis for markers such asIL-10,CXCL13,CD19, CD20 or flow cytometry (Baraniskinet al., 2011;Baraniskin & Schroers, 2014;Muñizet al., 2014;Rubensteinet al., 2013)." (PMID 39931233, 2019). "In conclusion, CSF CXCL13 is a useful diagnostic biomarker for patients with CNS lymphomas." (PMID 32314548, 2020). "We first evaluated the diagnostic utility of CSF CXCL13 in patients with CNS lymphomas." (PMID 32314548, 2020). "We confirmed that CSF CXCL13 is a useful diagnostic marker for patients with CNS lymphomas." (PMID 32314548, 2020). "However, CSF CXCL13 is a recently discovered diagnostic biomarker for CNS lymphoma." (PMID 32314548, 2020). "Because of this, CSF CXCL13 levels in primary CNS lymphoma, a diagnosis that can be difficult to make, can be very high and decrease with therapy; thus, CSF CXCL13 can potentially be utilized to assist in diagnosis and prognosis." (PMID 39766248, 2024). "By contrast, CXCL-13 CSF levels were extremely high (38,776 pg/ml) in a patient from group II; however, this patient suffered from primary CNS lymphoma at the time he acquired COVID-19." (PMID 35057809, 2022). "In the 14 patients with CNS lymphomas, the CSF concentrations of CXCL13 were measured after the completion of therapy." (PMID 32314548, 2020). "The ROC curve of the CSF CXCL13 levels for CNS lymphoma showed high sensitivity and specificity (AUC = 0.981)." (PMID 32314548, 2020). "In the first, we conducted a case‐control study (n = 248) demonstrating that the CSF CXCL13 concentration was significantly increased in CNS lymphoma patients compared with various other brain diseases (AUC = 0.981)." (PMID 32314548, 2020). "A comparison of the cerebrospinal fluid (CSF) concentrations of CXCL13 between CNS lymphomas and other CNS diseases." (PMID 32314548, 2020). "CXCL13 in combination with IL10 is upregulated in primary CNS lymphoma, and in this combination is specific for the disease." (PMID 31916298, 2020). "A relatively small study (n = 70) showed a significant difference in the CXCL13 levels between CNS lymphoma patients and control." (PMID 32314548, 2020). "In the present study, the CSF CXCL13 concentration was significantly increased in the patients with CNS lymphoma." (PMID 32314548, 2020). "The C‐X‐C motif chemokine ligand 13 (CXCL13) was recently reported to be another useful biomarker for CNS lymphoma." (PMID 32314548, 2020). "A relatively large study (n = 220) showed a high specificity of CSF CXCL13 level, and the combination of CXCL13 and IL‐10 is highly useful for the diagnosis of CNS lymphoma." (PMID 32314548, 2020). "Our study demonstrated that CNS lymphoma patients with high CSF CXCL13 levels had poorer OS and PFS." (PMID 32314548, 2020). "The mean concentrations of serum CXCL13 in CNS lymphoma and other diseases were 269 pg/mL (range 30‐938 pg/mL) and 217 pg/mL (range 1‐2070 pg/mL), respectively." (PMID 32314548, 2020). "The CXCL13 expression levels increased in the CNS lymphoma specimens compared with the other tumor specimens." (PMID 32314548, 2020). "The mean concentrations of CSF CXCL13 in CNS lymphoma and non‐CNS lymphoma were 1483 ± 731 and 55 ± 209 pg/mL, respectively." (PMID 32314548, 2020).
CNS lymphoma (continued). "While neither serum nor CSF CXCL12 levels differed between the CNS lymphoma patients and controls, CSF CXCL13 concentrations were significantly higher in the CNS lymphoma cohort, even as serum CXCL13 levels were consistently low in both groups." (PMID 28603659, 2016). "The CXCL12 and CXCL13 CSF/serum ratios were roughly similar to those reported in a recent analysis of CNS lymphoma." (PMID 24278364, 2013). "CXCL13 was over-production within the central nervous system (CNS) of CNS lymphoma patients, studies suggested that CXCL13 may as a potential biomarker of CNS lymphoma." (PMID 35452413, 2022). "To date, four studies analyzed CXCL13 CSF levels as biomarkers in CNS lymphoma." (PMID 33841320, 2021). "The CSF CXCL13 levels in CNS lymphoma were significantly higher than in the other CNS diseases." (PMID 32314548, 2020). "The CSF CXCL13 level is a useful prognostic factor for patients with CNS lymphoma." (PMID 32314548, 2020). "Given that CNS lymphoma cells express CXCR5, it is tempting to speculate about the role of CXCL13 in the pathogenesis of CNS lymphoma." (PMID 32314548, 2020). "In our case‐control study, CXCL13 was elevated in four cases in non‐CNS lymphoma." (PMID 32314548, 2020). "CXCR5, a receptor of CXCL13, was highly expressed in the CNS lymphomas." (PMID 32314548, 2020). "The CSF CXCL13 levels of CNS lymphoma were significantly higher than those of the other diseases." (PMID 32314548, 2020). "Furthermore, CXCL13 levels cannot differentiate between primary and secondary CNS lymphoma." (PMID 33841320, 2021). "Another relevant systematic review did not perform a formal meta-analysis on the diagnostic accuracy of the markers for CNS lymphoma in blood and CSF, and focused on various markers at the same time including CXCL13, interleukins-6, -8, and -10, soluble CD19, and so on, not just miRNAs." (PMID 34604087, 2021). "In addition, CSF CXCL13 was a prognostic biomarker for CNS lymphoma patients." (PMID 32314548, 2020). "The mean concentration of CXCL13 protein in CSF from newly diagnosed PCNSL and SCNSL was >50-fold higher than in CSF from patients without CNS lymphoma (p < 1 × 10−7)." (PMID 24969265, 2014). "It has been suggested that the sources of CXCL13 in the CNS are as follows: monocytes in LMN, macrophages infiltrating lesions, perivascular stromal cells in primary CNS lymphoma, microglial cells, or meningeal TLS in MS." (PMID 35892669, 2022). "CXCL13 protein that is known to mediate chemotaxis of CNS lymphoma cells was detected within biopsy specimens from PCNSL patients raising the possibility that this chemokine may contribute to CNS tropism." (PMID 33925295, 2021). "It is proposed, that the CNS source for CXCL13 are monocytes in LNB, lesion infiltrating macrophages, perivascular stromal cells in primary CNS lymphoma, microglia or meningeal TLS cells in MS." (PMID 32089130, 2020). "CXCL13 also occurs in CNS inflammation and is the focus of biomarker research for Lyme neuroborreliosis (LNB), CNS lymphoma, and multiple sclerosis (MS)." (PMID 32089130, 2020). "Further, we provide evidence that APRIL and BAFF induce chemotaxis of systemic and CNS lymphoma cell lines, confirming previously published results showing that BAFF increases the chemotactic response of human B cells to CXCL12, CXCL13, and CCL21 in vitro." (PMID 31615554, 2019). "In previous studies, CXCL13 was >50-fold higher in CSF in primary and secondary CNS lymphomas than in non-inflammatory controls." (PMID 38203597, 2023). "The serum CXCL13 levels of CNS lymphomas were not statistically increased compared with the other diseases, although the CSF CXCL13 levels were significantly increased in CNS lymphoma." (PMID 32314548, 2020). "From a clinical point of view, CXCL13 was again confirmed as a reliable marker for CSF B cell recruitment and might be used as a clinical marker to predict disease activity in MS, confirming the diagnosis of LNB and CNS lymphoma." (PMID 31727097, 2019).
CNS lymphoma (continued). "However, consensus has not been achieved because CXCL13 was found elevated in a broad spectrum of viral and bacterial infections, and immune-mediated and neoplastic CNS disorders, including varicella zoster virus facial palsy, neurosyphilis, MS, autoimmune encephalitis, and CNS lymphoma." (PMID 36078057, 2022).